STARD6 (StAR related lipid transfer domain containing 6)
Description:
May be involved in the intracellular transport of sterols or other lipids. May bind cholesterol or other sterols (By similarity).
Tractability: PROTAC: its protein half-life has been measured.
Gene: Protein-coding gene on chromosome 18 (54,324,358 to 54,357,964, reverse strand). Ensembl gene ENSG00000174448.
Pathways (Reactome):
Metabolism: Pregnenolone biosynthesis
Gene Ontology:
Molecular function: lipid binding
Genetic constraint (gnomAD): Loss-of-function variants: 8 observed, 12.67 expected, observed/expected ratio (o/e) 0.63, 90% interval 0.37 to 1.14. The upper end of that interval is the gene's LOEUF score, 1.14, which puts it in group 4 of 6, group 1 being the genes least tolerant of losing a copy. Missense variants: 176 observed, 196.16 expected, observed/expected ratio (o/e) 0.9, 90% interval 0.79 to 1.02. Synonymous variants: 52 observed, 67.33 expected, observed/expected ratio (o/e) 0.77, 90% interval 0.62 to 0.97.
Homologues: Orthologues: chimpanzee STARD6 (98% identical), macaque STARD6 (93% identical), rabbit STARD6 (85% identical), dog STARD6 (80% identical), pig STARD6 (76% identical), rat Stard6 (72% identical), mouse Stard6 (71% identical), guinea pig STARD6 (70% identical), tropical clawed frog stard6 (47% identical), Caenorhabditis elegans K02D3.2 (21% identical), Drosophila melanogaster Start1 (19% identical), Caenorhabditis elegans tag-340 (17% identical). Paralogues in human: STARD5 (29% identical), STARD4 (26% identical), STARD3 (22% identical), STAR (20% identical), STARD3NL (6% identical).
Diseases named in the same sentence as STARD6 in open-access papers:
STARD6 is named in the same sentence as 3 diseases in open-access papers, as found by Europe PMC text mining. Sharing a sentence is not in itself a finding about the gene and the disease.
STARD6 shares sentences with these, for which no sentence is quoted: cancer (1 paper); metastatic melanoma (1); metastatic tumors (1).